CARD9 (caspase recruitment domain family member 9)
Diseases named in the same sentence as CARD9 in open-access papers (continued):
Sharing a sentence is not in itself a finding about the gene and the disease.
tumor (31 papers, 2014 to 2026). "Treatment with Ly6G antibodies or the anti-fungal drug fluconazole can significantly improve tumor incidence in CARD9-deficient mice." (PMID 38169837, 2023). "Both studies showed that Card9-deficient mice were not only more susceptible to chemically induced colitis but also developed a higher tumor burden upon challenge with the carcinogenic agent axozymethane (AOM) followed by DSS (AOM–DSS)." (PMID 37294505, 2023). "In 2018, two studies reported that CARD9-deficient mice had increased tumor burden in the AOM/DSS-induced CRC mouse model, but the underlying mechanisms differed." (PMID 38169837, 2023). "Similar findings have been found in ESCC; high CARD9 expression was significantly associated with advanced tumor depth, positive lymph node metastases, and advanced stage." (PMID 35910636, 2022). "CARD9 (caspase recruitment domain family member 9) promotes metastasis‐associated macrophage polarisation, thereby promoting tumour metastasis." (PMID 35293027, 2022). "CARD9 contributes to tumour metastasis by promoting metastasis‐associated macrophage polarization through activation of the NF‐κB signaling pathway." (PMID 34734468, 2021). "Mechanistic studies revealed that CARD9 contributes to tumor metastasis through enhancing metastasis-associated macrophage polarization, independent of the number of infiltrating macrophages." (PMID 29352133, 2018). "In addition, CARD9 has been shown to be closely associated with CVDs, tumor formation and metastasis." (PMID 35432375, 2022). "Moreover, the rate of tumor cell proliferation was decreased in CARD9-deficient mice, and the tumor cell-intrinsic activation of STAT3 was substantially reduced." (PMID 30906296, 2019). "Then, we identified YY1 as a critical upstream transcription factor that bound to the promoter of CARD9 and repressed it, accompanied with DC dysfunction and tumor growth." (PMID 42212326, 2026). "Experimental models have shown that fungal overgrowth exacerbates CRC in CARD9-deficient mice, whereas antifungal treatment with fluconazole reduces MDSC infiltration and suppresses tumor development." (PMID 41163402, 2025). "The expression of CARD9 was lower in tumor tissues than it was in the normal groups for GSE28735 and GSE62452 (p < 0.05) cohorts." (PMID 37727377, 2023). "Candida tropicalis proliferates in CARD9-deficient mice, thereby inducing the differentiation and activation of MDSC cells, mainly G-MDSC, which is conducive to tumor immune evasion." (PMID 38169837, 2023). "The clinicopathologic analysis shows that CARD9 expression is positively correlated with tumor invasion and metastasis." (PMID 35432375, 2022). "The tumor burden is significantly increased in Lewis lung cancer mouse model after CARD9 deletion, accompanied with accumulation of MDSCs and reduction of CTL." (PMID 35432375, 2022). "CARD9 is likely to play an essential role in regulating the tumor microenvironment, which will be the focus of our future research." (PMID 36443670, 2022). "A study discovered that CARD9 was a crucial regulator of tumor formation and a promising therapeutic target for lung cancer." (PMID 36443670, 2022). "Recent studies revealed that CARD9 signaling can contribute to both tumor-promoting and tumor-suppressive immunity in the intestine, and these distinct effects are strongly influenced by the composition of the microbiota." (PMID 30906296, 2019). "CARD9 can activate the NF-κB pathway, which is critical to inflammation but also tumor cell survival, migration and proliferation." (PMID 31675375, 2019). "In the context of pVHL loss, CARD9 silencing led to a sharp reduction in TRAF6, which was known to function upstream of JNK, retarding tumor growth." (PMID 29352133, 2018). "CARD9 polarized macrophages toward a M2 phenotype in the tumor microenvironment by NF-κB activation." (PMID 29352133, 2018).
tumor (continued). "CARD9-dependent signaling in tumor development and metastasis has been revealed in several recent studies using animal models and cell lines." (PMID 30127791, 2018). "CARD9 is highly expressed by tumor-infiltrating macrophages and has been shown to be a critical modulator of the polarization of these cells toward a highly inflammatory metastatic-inducing phenotype." (PMID 30127791, 2018). "CARD9 had been shown to play a key role in APCmin tumor incidence and progression, markedly reducing viability and promoting colonic tumorigenesis in male mice." (PMID 29352133, 2018). "Mechanistically, GLP promoted the differentiation of myeloid-derived suppressor cells (MDSCs) and inhibited MDSC accumulation in spleen and tumor tissues through the caspase recruitment domain-containing protein 9 (CARD9)/nuclear factor-κB (NF-κB)/indoleamine 2,3-dioxygenase (IDO) signaling pathway." (PMID 35865946, 2022). "However, CARD9 has also been shown promoting tumor effects in various types of malignant diseases, including CAC." (PMID 35619716, 2022). "CARD9 is also involved in tumor metastasis through regulation of macrophage polarization." (PMID 35432375, 2022). "Moreover, CARD9 knockout (CARD9–/–) mice had increased tumor loads and the accumulation of MDSCs in tumor tissue." (PMID 35910636, 2022). "It is reported that CARD9 is highly expressed in the infiltrated macrophages during carcinoma progression with enhanced production of tumor-promoting cytokines (IL-10 and IL-1α), and decreased production of anti-tumor cytokine IL-12, thus, contributing to tumor metastasis." (PMID 35432375, 2022). "Interestingly, CARD9 as an inflammation-related gene also promote the proliferation and migration of tumor cells, induce cancer, and affect tumor severity and prognosis." (PMID 29352133, 2018). "Consequently, VHL-deficient cancer cells failed to phosphorylate CARD9, resulting in constitutive activation of CARD9, an upstream trigger for NF-κB activation to induce tumor occurrence." (PMID 29352133, 2018). "This may account for the dual functions of CARD9 that is a tumor promoter and/or tumor inhibitor." (PMID 37727377, 2023). "There may be a sex difference in the role of CARD9 in tumor biology." (PMID 35432375, 2022). "Notably, the deficiency of Dectin-3 or the CARD9/SYK axis in dendritic cells and macrophages resulted in a fungal dysbiosis represented by an increase of C. tropicalis, which subsequently led to an accumulation of MDSC, thus promoting tumor progression." (PMID 36131933, 2022). "Thus, it is possible that ectopic expression of Rad50 may recruit CARD9 and contribute to tumour metastasis through activating NF‐κB pathway in HGSOC." (PMID 34734468, 2021). "CARD9 was equally immunoprecipitated from total cell protein lysates of each group, but Bcl10 and MALT1 attached to CARD9 increased nearly 2 and 3 folds respectively on NLGP addition to the tumor-conditioned cells, suggesting the trimolecular complex formation because of the NLGP-transduced signal." (PMID 38649988, 2024). "In the GSE15471 cohort, the expression of CARD9 was higher in tumor tissues but with no statistical significance." (PMID 37727377, 2023). "In cancer, the cellular location of CARD9 is in tumor-infiltrating macrophages rather than in cancer cells, which explains the lower expression of CARD9 in PC cells and samples than in normal pancreatic ones." (PMID 37727377, 2023). "Furthermore, tumour tissues showed significantly decreased expression of cytoplasmic microbial sensors (NOD1 and NOD2) and downstream signaling molecules for innate microbial sensors such as CARD6, CARD9, and TRAF6 (p = 0.0207, p = 0.0040, and p = 0.0119, respectively)." (PMID 37007104, 2023).
cancer (16 papers, 2014 to 2025). A tumor composed of atypical neoplastic, often pleomorphic cells that invade other tissues. "Genome-wide association studies have showed that functional loss of Card9 is related to the development of inflammatory disease and cancer." (PMID 35618701, 2022). "Notably, OTUD1 has been implicated in modulating antifungal innate immunity through the deubiquitination of CARD9, while its deficiency in various human cancers is strongly linked to cell survival, apoptosis, and the inhibition of cancer progression by triggering immunogenic cell death." (PMID 40007014, 2025). "In conclusion, as an important adapter molecule in fungal immunity, CARD9 exhibits pro- and anti-cancer properties." (PMID 35910636, 2022). "CARD9 deletion reduces tumorigenic potential of VHL-defective cancer cells with normalization of NF-κB activity and preserved sensitivity of cytokine-induced apoptosis." (PMID 35432375, 2022). "Collectively, these studies provide the intriguing possibility that inappropriate CARD9 activation contributes to the development of certain cancers and may be a novel target of future therapies for these diseases." (PMID 30127791, 2018). "Ganoderma lucidum polysaccharides have recently been exploited as potential components in the treatment of cancer, which induce the differentiation of MDSCs and inhibit their accumulation by activating the CARD9-NF-κB-IDO pathway in Lewis lung cancer, thereby preventing cancer progression." (PMID 39605905, 2024). "FERMT1, MET, and MMP3 overexpressed in PC tissues, while the expressions of CARD9 were not outstanding in both normal and cancer tissues in PC." (PMID 37727377, 2023).
bacterial infection (9 papers, 2016 to 2024). "In bacterial infections, a CARD9 deficiency results in a decrease in inflammatory cytokines (IL-1β, IL-6, and TNF-α) and chemokines (CXCL1, CXCL2, and CXCL5)." (PMID 38473845, 2024). "CARD9 is involved in immune signaling linked to bacterial infections through TLRs (TLR2 and TLR4) and NLRs (NOD1 and NOD2)." (PMID 38473845, 2024). "M.tb has previously been shown to inhibit inflammasome activation and IL-1β processing, and a recent study demonstrated that CARD9, an inflammasome protein associated with fungal induction of proinflammatory cytokines, negatively regulated IL-1β production during bacterial infection." (PMID 36591308, 2022). "CARD9 is essential for NF-κB activation, mediates intestinal repair, T-helper 17 responses, and control of bacterial infection after intestinal epithelial injury." (PMID 37685869, 2023). "Polarization to the Th17 lineage also depends on CARD9 in the context of gastrointestinal (GI) bacterial infection, similar to what has been described for the generation of Th17 responses in the fungal-infected oral mucosa." (PMID 30127791, 2018). "Our data suggest that, in addition to the well-described regulatory role for CARD9 downstream of SYK, it is also possible that CARD9 can act upstream of SYK during bacterial infection." (PMID 27670879, 2016). "In this study we have identified a new role for CARD9 as a negative regulator of IL-1β production in response to bacterial infection." (PMID 27670879, 2016). "In conclusion we have identified a novel negative regulatory role for CARD9 on IL-1β production in macrophages by modulating pro-IL-1β expression and caspase-8 recruitment to the inflammasome in response to bacterial infection." (PMID 27670879, 2016). "Similarly, in immune responses to bacterial infection and CLR ligands, a CARD9 deficiency leads to reductions in Th1 and Th17 cytokines." (PMID 38473845, 2024). "Little is known about whether CARD9 is important in regulating the host response to bacterial infection." (PMID 27670879, 2016). "Thus, animal models have demonstrated that Card9 can play distinct protective roles in immunity to intracellular bacterial pathogens, however, the relevance of these functions in humans remains to be determined given that CARD9-deficient patients do not appear susceptible to bacterial infections." (PMID 30127791, 2018). "Here we show that caspase recruitment domain-containing protein 9 (CARD9), a protein associated with induction of proinflammatory cytokines by fungi, has a negative role on IL-1β production during bacterial infection." (PMID 27670879, 2016).
infectious disease (6 papers, 2016 to 2023). A disorder directly resulting from the presence and activity of a microbial, viral, or parasitic agent in humans. "Mutation and genetic polymorphisms of CARD9 are reported to be correlated with a wide range of infectious diseases in human." (PMID 35432375, 2022). "Because of the critical role of CARD9 in the production of inflammatory cytokines and chemokines during initiation of innate immunity and later adaptive immunity, mutation and genetic polymorphisms of CARD9 are reported to be correlated with a wide range of infectious diseases in humans." (PMID 35432375, 2022). "The function of CARD9 in infectious diseases seems to be clearly context-dependent and varies among different pathogens, disease phases and affected organ systems." (PMID 34209576, 2021). "Although a general consensus concerning the role of CARD9 expression in infectious diseases has been reached 3, 22, 23, its role in diet‐induced inflammation and metabolic disorders is still less obvious." (PMID 29575791, 2018). "Although a general consensus concerning the role of CARD9 expression in infectious diseases has been reached, its role in sterile‐induced inflammation is still less obvious." (PMID 27957800, 2017). "It was becoming clear that Card9 contributed to innate immune response against these infectious diseases." (PMID 26893103, 2016).
cardiovascular diseases (4 papers, 2022 to 2024). "CARD9 is a potential target for the treatment of cardiovascular diseases by regulating autophagy." (PMID 35733381, 2022). "CARD9 acts as a therapeutic target for cardiovascular diseases by regulating autophagy." (PMID 35733381, 2022).
metabolic disorders (4 papers, 2018 to 2023). "CARD9 knockout may ameliorate the metabolic disorders and inflammatory response in insulin susceptible organs in mice after 8–12 weeks of HFD feeding." (PMID 29575791, 2018). "Together, these findings implicated novel roles for CARD9 in islet dysregulation under hyperglycemic stress, further affirming roles for CARD9 in the pathology of metabolic diseases." (PMID 37958977, 2023). "CARD9-mediated signaling was shown to be involved in diet-induced inflammation and cardiac dysfunction as well as metabolic disorders and ischemia/reperfusion cardiac injury." (PMID 36860276, 2023). "In this study, CARD9−/− and C57BL/6 mice were fed with HFD to establish obese animal model to evaluate the impact of CARD9 on diet‐induced inflammation and metabolic disorders, and to explore the potential mechanism of CARD9 in mediating energy metabolism." (PMID 29575791, 2018). "The results indicated that CARD9 deficiency very likely alleviates the HFD‐induced inflammation and metabolic disorders through inactivating the MAPKs and NF‐κB signalling pathways." (PMID 29575791, 2018). "Thus, it is likely that the principal effect of CARD9 knockout on ameliorating metabolic disorder and inflammation of WAT and liver is mediated by down‐regulation of the p38 MAPK signalling pathway‐mediated inflammation." (PMID 29575791, 2018). "Thus, the CARD9 knockout‐related inhibition of NF‐κB and P38 MAPK activity is likely to be a useful approach in alleviating the inflammatory response in diet‐induced metabolic disorders." (PMID 29575791, 2018). "In conclusion, our results suggested that CARD9 could have a new functional role in mediating energy metabolism, insulin resistance and inflammatory response in diet‐induced inflammation and metabolic disorders, which is likely independent of the innate immunity." (PMID 29575791, 2018).
cardiac disease (2 papers, 2022 to 2023). "To date, our understanding of the role of CARD9 signaling-mediated inflammatory responses in infectious or aseptic cardiac diseases is consistent, indicating that CARD9 contributes to proinflammatory effects." (PMID 35173530, 2022).
kidney disease (1 paper, 2022). "Our study is the first to investigate the role of CARD9 in kidney disease." (PMID 35733381, 2022).
neurological disease (1 paper, 2023). "To explore a potential role for CARD9 in Alzheimer’s-related disease, we crossed CARD9-deficient mice with 5xFAD mice, a well-described mouse model of Aβ-mediated neurological disease." (PMID 37276426, 2023). "Collectively, these findings uncover CARD9 as a molecular signaling molecule used by the innate immune system in Aβ-mediated neurological disease." (PMID 37276426, 2023). "Taken together, these findings indicate that the innate immune signaling molecule CARD9 is a regulator of Aβ-mediated neurological disease and further suggest that targeting CARD9 activation may offer a therapeutic strategy to promote Aβ clearance." (PMID 37276426, 2023).
CARD9 also shares sentences with these, for which no sentence is quoted: mycoses (5 papers); ankylosing spondylitis (4); pancreatic cancer (3); allergic bronchopulmonary aspergillosis (2); Alzheimer disease (2); clear cell renal carcinoma (2); deep dermatophytosis (2); Glucose intolerance (2); inflammation (2); leukemia (2); mucormycosis (2); neurodegenerative disease (2); type 1 diabetes (2); acute kidney injury (1); acute respiratory distress syndrome (1); adult onset immunodeficiency syndrome (1); asthma (1); autoimmune glomerulonephritis (1); Autosomal dominant hyper-IgE syndrome (1); cardiomyopathy (1); carditis (1); cerebral malaria (1); Cholecystitis (1); cholelithiasis (1); chronic lung allograft dysfunction (1); Cirrhosis (1); combined immunodeficiency (1); diabetic cardiomyopathy (1); enteritis (1); epidermolysis bullosa acquisita (1).
A further 26 diseases each share a sentence with CARD9 in 1 paper.